CDKN2A (cyclin dependent kinase inhibitor 2A)
Diseases named in the same sentence as CDKN2A in open-access papers (continued):
Sharing a sentence is not in itself a finding about the gene and the disease.
tumor (continued). "Epigenetic variations observed within the CDKN2A gene, engendered by exogenous environmental elements, exemplify the paradigmatic mechanisms of tumor formation instigated by external environmental factors through the genesis of heterotypic cells." (PMID 39440184, 2024). "This is one possible explanation for the short response in our patient who has co‐mutations identified in the initial tumour sample at diagnosis including NTRK1 over‐expression, TERT gain of function mutation and CDKN2A and CDKN2B loss." (PMID 39188081, 2024). "Recently, it has been reported that PRAME forms a complex with p14/alternate reading frame (ARF) (CDKN2A), a well-established tumor suppressor, as well as with Cullin 2 RING E3 ligases." (PMID 38132219, 2023). "The P16 gene (p16INK4a or CDKN2A or INK4/ARF locus) is located on 9p21 chromosome and acts as a tumor-suppressor gene." (PMID 36982734, 2023). "In AT, besides its cell cycle regulator functions (i.e., anti-proliferative and tumor suppressor), the CDKN2A locus also controls the commitment of stem cells to the brown-like type fate and mature adipocyte energy metabolism." (PMID 36980212, 2023). "These alterations also inhibit the cell cycle regulation roles of CDKN2A which allows for tumor initiation." (PMID 37626750, 2023). "CDKN2A is a tumor suppressor gene playing a central role in the regulation of the cell cycle and induction of apoptosis." (PMID 38201484, 2023). "This suggests that signaling pathway genes co-opt both promoters, where tumor cells utilize signaling pathways differently via alternative promoter usage (for example in CDKN2A and ERBB2)." (PMID 37169774, 2023). "Through a comprehensive analysis of multiple omics data from over 10,000 samples across 33 tumour types, it was found that CDKN2A is the copper death regulator with most frequent occurrences of somatic mutations." (PMID 37801050, 2023). "Another tumor suppressor involved in entosis is CDKN2A, a cell cycle regulator and tumor suppressor gene in external cells." (PMID 37790755, 2023). "CDKN2A is categorized as a major tumor suppressor gene where the genetic and epigenetic alterations that usually occur to that gene can be correlated with poor patient survival in different types of human tumors." (PMID 37626750, 2023). "Mining the correlation between CDKN2A mRNA expression and clinicopathological features, including tumor status, distant metastasis, and pathological stage, as well as related molecular gene expression, is of great significance in diagnosing and treating CRC." (PMID 37950153, 2023). "After the assessment of CDKN2A genetic alterations, it was important to explore the epigenetic modifications that occur in CDKN2A to control its expression under tumor conditions." (PMID 37626750, 2023). "After exploring the differential transcriptional levels of CDKN2A in cancerous and normal tissue and observing the upregulation of CDKN2A under tumor conditions, we aimed to study the protein levels to investigate if a similar pattern will be found." (PMID 37626750, 2023). "It was found that CDKN2A expression was related to clinicopathological features such as inflammation and tumor stage." (PMID 37950153, 2023). "Previous studies in multiple cancers have identified a role for oncogenes, including CDKN2A, also called p16, as regulators of a range of tumor cell processes directly and indirectly contributing to the regulation of many different metabolic pathways." (PMID 36841765, 2023). "Initial studies described the relationship between CDKN2A/B and biologic markers of tumour aggressiveness (tumour grade and Ki-67 index)." (PMID 37504251, 2023). "In this analysis, we found that the expression of FDX1, GLS, and CDKN2A increased when the tumor progressed from the T2 stage to the T3 stage." (PMID 37711156, 2023).
tumor (continued). "Previous studies revealed that cyclin dependent kinase inhibitor 2A (CDKN2A) played an important role in oncogenesis and tumor progression." (PMID 36845727, 2023). "CDKN2A is a tumor suppressor gene on chromosome 9p21.3 that plays a role in tumor proliferation suppression." (PMID 36843949, 2023). "Next, a detailed profile of CDKN2A genetic alteration under tumor conditions was described and assessed for its effect on the status of different human immune components." (PMID 37626750, 2023). "Compared with adjacent non-tumor tissues, CDKN2A, DLAT, and PDHA1 protein expression was upregulated in HCC tissues." (PMID 38078880, 2023). "To illustrate the expression distribution of CDKN2A in tumor microenvironment, we also visualized the expression of CDKN2A in different cells using the TISCH webtool." (PMID 36961395, 2023). "CDKN2A is a typical tumor suppressor gene, which can regulate the physiological activities of cancer cells in many ways." (PMID 37878133, 2023). "We found that FDX1, DLD, PDHA1, MTF1, GLS, and CDKN2A showed differential expression levels between normal and tumor tissues." (PMID 37711156, 2023). "Moving to the promoter methylation level assessment, almost all of the analyzed tumors with a significant score (p-value < 0.05) demonstrated hypermethylation of CDKN2A under tumor conditions in comparison to normal samples." (PMID 37626750, 2023). "We first analyzed the differential expression of 14 CRCGs in five GEO datasets, and the results displayed that SLC25A5 and CDKN2A were significantly up-regulated in tumor samples." (PMID 36980514, 2023). "CDKN2A, a tumor suppressor gene, is inactivated by homozygous deletions with high frequency in a variety of human primary tumors." (PMID 38134090, 2023). "We uncovered that Cdkn2a deletion, the most common secondary mutation in EHE tumours, permitted senescence bypass and increased cell growth." (PMID 37296967, 2023). "Homozygous CDKN2A/B deletion (HR: 8.4, 95% CI 6.4–11.0, p < 0.00001) was found to be significantly correlated with tumor progression." (PMID 38017560, 2023). "Our research can provide some clues for further research on the potential role of CDKN2A in tumor immunotherapy for exploration and practical application." (PMID 36961395, 2023). "Three shared somatic mutation genes were identified between the tumor and the CSF, namely TERT, PI3KCB, and CDKN2A." (PMID 37822669, 2023). "In tumor tissues, the abundance of CDKN2A and MTF1 were higher, as well as the levels of DLD, FDX1, GLS, LIPT1 and PDHB were down-regulated." (PMID 37662947, 2023). "This difference seems unrelated to primary tumor grade (five/six grade 2/3 tumors developed a CDKN2A/RB1 alteration upon progression to grade 4 vs. six/six grade 2/3 tumors without progression-related alteration, respectively, p = 1.0, Fisher’s exact test)." (PMID 37932833, 2023). "Most of these genes are reported to be involved in either lymphoid development (such as PAX5 and IKZF1), lymphoid signaling, cell cycle and apoptosis regulation (mostly tumor suppressors such as CDKN2A), DNA repair, therapy response, or transcription factors." (PMID 36980958, 2023). "Two important tumor suppression genes, CDKN2A, and CDKN2B, are transcribed from 9p21.3, the deletion of which contributes to tumorigenesis and tumor development, including GC." (PMID 37319315, 2023). "The results demonstrated that the expression of MTF1 was down-regulated while the level of CDKN2A was up-regulated in tumor tissues." (PMID 37662947, 2023).
tumor (continued). "CDKN2A acts as a tumor suppressor, meaning that it helps to regulate cell growth and prevent the development of cancer." (PMID 37504268, 2023). "Several SNPs at the CDKN2A / 2B site lessen their expression and result in tumor cell proliferation and progression." (PMID 37845622, 2023). "According to our research, CDKN2A is a stable biomarker of tumor prognosis, which can effectively predict the response of immunotherapy and is closely related to tumor immune microenvironment." (PMID 36961395, 2023). "Eight (16%) of the 50 tumours with available CDKN2A/B data demonstrated homozygous deletion; while these patients had slightly shorter survival (HR 1.37), the difference was not statistically significant (95% CI 0.41–2.08, p=0.571)." (PMID 37316586, 2023). "Histological grading and MRI assessment both assess the current status of the tumour, while CDKN2A/B homozygous deletion instead indicates a likelihood of more rapid progression down the track." (PMID 37316586, 2023). "One of the basic points for analysis in the current study and other CDKN2A-related reports was the analysis of CDKN2A genetic and epigenetic alterations under tumor status." (PMID 37626750, 2023). "As an example, SVs can affect tumour suppressors, including SMAD4 and CDKN2A, by causing homozygous deletion or inactivating alterations." (PMID 36765737, 2023). "Cells in each of the 22 clusters expressed variable levels of p16Ink4a (Cdkn2a) however, only malignant tumor cells expressed high levels of p16Ink4a." (PMID 36707509, 2023). "On univariate analysis, CDKN2A/B co-deletion, number of brain metastases present at surgery, tumor volume, increased time from brain met diagnosis to surgery, and prior intracranial radiation were associated with decreased time to distant progression." (PMID 36915611, 2023). "In epithelial cells, FDX1 and DLD were highly expressed in all kinds of cells, and CDKN2A was mainly expressed in tumor." (PMID 37239416, 2023). "Alterations in genes involved in cell cycle regulation mediated by CDKN2A/2B were identified in 78.1% of GBM tumor samples." (PMID 38143440, 2023). "Molecular genetic analysis of the tumor revealed an isocitrate dehydrogenase (IDH) mutation p.R132H (c.395C>A) mutation in the IDH1 gene and a heterozygous duplication of the CDKN2A genes." (PMID 37374260, 2023). "As a tumor suppressor, CDKN2A can affect tumor development when silenced by deletion, methylation, or other mechanisms." (PMID 36936439, 2023). "But since the issue of the immune microenvironment and CDKN2A abnormality in EPN-ZFTA, and its association with the prognosis of the tumor, are surely interesting, it awaits further studies in the future." (PMID 37322295, 2023). "CDKN2A was shown to be the most common secondary mutation in EHE, conferring increased tumour aggressiveness." (PMID 37980390, 2023). "Our findings suggest such antagonism extends to tumor suppression in mammalian cells, likely via regulation of Cdkn2a and other tumor suppressor genes." (PMID 37261974, 2023). "Matched tumor-normal NGS with FACETS analysis detects a range of prognostically relevant alterations in CDKN2A/B and other genes." (PMID 37831210, 2023).
tumor (continued). "Here, we present a case of a patient with advanced SqCLC that harbors not only CDKN2A mutation, and PIK3CA amplification, but also Tumor mutational burden High (TMB-H) and a tumor proportional score (TPS) of 50%." (PMID 36835617, 2023). "Cyclin-dependent kinase inhibitors 1A and 2A (CDKN1A and CDKN2A) have been identified as ferroptosis-related genes in recent studies and can be regarded as biomarkers that influence the tumor microenvironment." (PMID 36900015, 2023). "We found that DLD, DLAT, PDHA1, and CDKN2A were differentially expressed between normal and tumor tissues; CDKN2A was upregulated and the other genes were downregulated in the tumor tissues." (PMID 37711156, 2023). "In order to identify the pivotal genes in regulating CRG subgroup division and tumor-immunity-mediated drug sensitivity change, an importance analysis is performed, and it shows CDKN2A is the most important gene." (PMID 37857018, 2023). "Among patients with best response progressive disease (N = 6), 5 had grade 4 tumor and 4 had known CDKN2A alteration." (PMID 36968138, 2023). "Examples of cases initially overscored in the blinded analysis included a tumor with CDKN2A HD, which showed retained p16 staining in scattered entrapped non-neoplastic cells." (PMID 37138345, 2023). "Matching with that, we found promoter hypermethylation of CDKN2A in tumor tissue as an epigenetic control method to inhibit the expression of the “normal” functioning CDKN2A tumor suppressor gene in the tumor tissue." (PMID 37626750, 2023). "The first stage of the current study was the analysis of CDKN2A differential expression in tumor tissues and the corresponding normal ones and correlating that with tumor stage, grade, metastasis, and clinical outcome." (PMID 37626750, 2023). "Some genes were differentially expressed not only between normal and tumor samples, but also in tumor samples (CDKN2A; Solute Carrier Family 2 Member 1, SLC2A1)." (PMID 37239416, 2023). "At present, CDKN2A has been deeply studied in genomics and signaling pathway of specific malignant tumors, but its research on specific types of tumor immunity is less, and the research on pan-cancer immunity is even shallower." (PMID 36961395, 2023). "CDKN2A was often regarded as a tumor suppressor and approximately 8% of HCC patients harbored CDKN2A deletions." (PMID 37464443, 2023). "While specific loci such as the CDKN2A locus have been pointed out as key sites of retained H3K27me3 in data from both tumor subtypes, more global analyses of the similarities and differences in H3K27me3 landscapes in these tumors are lacking." (PMID 36759899, 2023). "While CDKN2A showed a surprisingly dominant role in mediating the tumor-suppressive effects of the broadly acting MLL3 enzyme, there are precedents for a predominant contribution of a single gene to the functional output of chromatin-complex disruption." (PMID 37261974, 2023). "The proteins that are encoded by CDKN2A (p16INK4A and p14ARF) and CDKN2B (p15INK4B) regulate the cell cycle and apoptosis and thus play the role of the tumor suppressor." (PMID 37908227, 2023). "They reported an increasing frequency of CDKN2A deletions with grade (0% in grade 2, 14.3% in grade 3, and 27.3 in grade 4 tumours)." (PMID 37504251, 2023). "p16 (CDKN2A) deletions, one of the frequent early events during cancer evolution, were enriched in tumours with high proportions of cells in G0." (PMID 37221612, 2023). "CDKN2A (also called p16) was an important tumor suppressor that prevents carcinogenesis through induction of senescence cell growth and arrest (Rayess, Wang & Srivatsan, 2012)." (PMID 37041979, 2023).
tumor (continued). "It has been reported that the expression of CDKN2A, GLS and LIPT1 is positively correlated with the abundance of CD8+T cells and neutrophils and CDKN2A expression positively correlated with the degree of tumor infiltration, which was in line with our study." (PMID 36843949, 2023). "SLC25A5 and CDKN2A were found to be significantly up-regulated in tumor samples after we conducted differential analysis on these 14 CRCGs." (PMID 36980514, 2023). "Here, we present the course of diagnosis and treatment of a patient with advanced SqCLC, harboring not only CDKN2A mutation but also PIK3CA amplification, Tumor Mutational Burden-High (>10 mutations/megabase), and a Tumor Proportion Score of 80%." (PMID 36835617, 2023). "8/50 tumours with CDKN2A/B results demonstrated homozygous deletion; slightly shorter survival was not significant (p=0.571)." (PMID 37316586, 2023). "CDKN2A is a gene that belongs to the category of tumor suppressor genes and the malfunction of these genes participates in tumor initiation." (PMID 37626750, 2023). "Here, we combined genetic, epigenomic, and animal modeling approaches to demonstrate that one of the mechanisms by which MLL3 links chromatin remodeling to tumor suppression is by co-activating the Cdkn2a tumor suppressor locus." (PMID 37261974, 2023). "Copy number losses containing the region including CDKN2A/2B were seen exclusively in the higher grade tumours from patients C (C2, C5, C6, C7) and F (F2, F4: replicates)." (PMID 36882706, 2023). "Collectively, CD8 T cell infiltration and exhaustion status, CCL4 and CCR6 expression are different immune components that were affected by the CDKN2A genetic alterations in a way that finally enables tumor growth and progression." (PMID 37626750, 2023). "The state of CDKN2A hypermethylation and inactivation under tumor conditions predicts different adverse events." (PMID 37626750, 2023). "It is repeatedly reported that tumor suppressor genes suffer from genetic alterations under the tumor conditions, therefore the cBioPortal database was utilized to investigate CDKN2A genetic alterations." (PMID 37626750, 2023). "Mutations in CDKN2A are more common in MIBC, but have recently been identified in normal urothelium and tumor specimens from NMIBC patients and deletion was associated with progression in NMIBC." (PMID 37175559, 2023). "On one hand, CDKN2A is a critical tumor suppressor that induces cell cycle arrest by inhibiting the CDK4/6-Cyclin D complex upon activation." (PMID 37665670, 2023). "The most prominent homozygous deletions in cancer affect chromosome 9p21.3 and eliminate CDKN2A/B tumour suppressors, disabling a cell-intrinsic barrier to tumorigenesis." (PMID 38024139, 2023). "Further, we found that FDHA1 was downregulated and CDKN2A was upregulated in clinical tumor samples, which was consistent with the results from the public databases." (PMID 37711156, 2023). "Whole-exome sequencing revealed 99 somatic mutations including SMARCA4, ARID2, TET2, CDKN2A, WNT7A, NOTCH3 and STAG2, all present both in the primary tumor and in the cell line." (PMID 38201285, 2023). "The tumor was WHO grade 2–3 and next-generation sequencing was notable for TERT promoter mutation, homozygous deletion of CDKN2A, and high variant allele frequency of NF2." (PMID 37025757, 2023).